USP27X (ubiquitin specific peptidase 27 X-linked)
Description:
Deubiquitinase involved in innate antiviral immunity by mediating deubiquitination of CGAS and RIGI. Negatively regulates RIGI by mediating 'Lys-63'-linked deubiquitination of RIGI, inhibiting type I interferon signaling. Also regulates 'Lys-63'-linked ubiquitination level of MDA5/IFIH1. Acts as a positive regulator of the cGAS-STING pathway by catalyzing 'Lys-48'-linked deubiquitination of CGAS, thereby promoting its stabilization. Can reduce the levels of BCL2L11/BIM ubiquitination and stabilize BCL2L11 in response to the RAF-MAPK-degradation signal (By similarity). By acting on BCL2L11 levels, may counteract the anti-apoptotic effects of MAPK activity (By similarity).
Synonyms: USP22L; USP27; MRX105; XLID105
Tractability: PROTAC: ubiquitination databases record sites on it.
Target class: Enzyme; Hydrolase
Gene: Protein-coding gene on chromosome X (49,879,484 to 49,882,558, forward strand). Ensembl gene ENSG00000273820.
Subcellular location: Cytoplasm, cytosol; Nucleus
Subcellular location (Human Protein Atlas): Vesicles; Nucleoplasm
Gene Ontology:
Molecular function: cysteine-type deubiquitinase activity; cysteine-type endopeptidase activity; K48-linked deubiquitinase activity; K63-linked deubiquitinase activity; cysteine-type peptidase activity
Biological process: defense response to virus; positive regulation of type I interferon-mediated signaling pathway; protein K48-linked deubiquitination; protein stabilization; positive regulation of apoptotic process; protein deubiquitination; protein K63-linked deubiquitination
Cellular component: nucleus; cytosol
Gene-disease validity (ClinGen):
ClinGen rates the evidence that USP27X causes each of these diseases.
X-linked intellectual disability (X-linked): Limited. An X-linked intellectual deficiency in which not enough information is known, reported or published to indicate whether a gene causes non-syndromic or syndromic presentations.
Homologues: Orthologues: macaque USP27X (100% identical), guinea pig USP27X (99% identical), pig USP27X (99% identical), rabbit USP27X (97% identical), rat Usp27x (97% identical), mouse Usp27x (96% identical). Paralogues in human: USP22 (80% identical), USP51 (71% identical), USP19 (28% identical), USP15 (27% identical), USP33 (27% identical), USP4 (26% identical), USP16 (26% identical), USP2 (26% identical), USP20 (26% identical), USP44 (26% identical), USP45 (26% identical), USP11 (25% identical), and 59 more.
Diseases named in the same sentence as USP27X in open-access papers:
USP27X is named in the same sentence as 19 diseases in open-access papers, as found by Europe PMC text mining. Sharing a sentence is not in itself a finding about the gene and the disease. The quoted sentences say what the papers report.
hepatocellular carcinoma (5 papers, 2020 to 2025). A malignant tumor that arises from hepatocytes. "For example, USP27X has been implicated in promoting cell proliferation and invasion in hepatocellular carcinoma (HCC) and colorectal cancer (CRC)." (PMID 38030604, 2023). "Ubiquitin specific peptidase 27 X-linked divergent transcript (USP27X-DT, formerly named USP27X-AS1) was reported to bind with serine and threonine kinase AKT and upregulate AKT signaling in hepatocellular carcinoma." (PMID 41387767, 2025).
breast carcinoma (3 papers, 2020 to 2023). "Depletion of USP22, USP51, or USP27X inhibits breast cancer growth partly through downregulation of H2Bub1." (PMID 34575114, 2021). "It has been demonstrated that USP27X is a putative deubiquitinase for Snail1, which enhances breast cancer cells resistance to cisplatin via stabilizing Snail1 and at least reinforcing repression of apoptosis associated genes." (PMID 34575114, 2021). "Specifically, DUB3 was shown to respond to IL-6-stimulated transcriptional activation and stabilize Snail1 in breast cancer cells; while USP27X expression was reported to be induced by TGFβ, which assisted the upregulation of Snail1 and other mesenchymal genes." (PMID 32968046, 2020). "Clinically, the co-expression of high levels of USP27X and CBX2 in breast cancer tissues is indicative of a poor prognosis for patients with this disease." (PMID 38030604, 2023). "It is believed that imbalances of USP22, USP27X, and USP51 lead to SAGA-related breast cancer development." (PMID 34575114, 2021).
lung carcinoma (3 papers, 2020 to 2023). "On one hand, the downregulation of USP27X in lung carcinoma cells has been demonstrated to enhance their sensitivity to cisplatin therapy." (PMID 38030604, 2023). "Conversely, USP27X has been suggested to exert tumor-suppressive effects in ovarian and lung cancer by inhibiting cell growth and metastasis." (PMID 38030604, 2023).
Autoimmunity (1 paper, 2020). The occurrence of an immune reaction against the organism's own cells or tissues. "USP27X may also contribute to the autoimmunity through increasing cell death by apoptosis." (PMID 33297945, 2020). "Given that the possible implication of USP27X in the autoimmunity has not been addressed in any studies, however, a hypothetical implication of USP27X in the autoimmunity can be deduced from the other studies." (PMID 33297945, 2020).
melanoma (1 paper, 2022). A malignant, usually aggressive tumor composed of atypical, neoplastic melanocytes. "We followed up on this observation and report here that overexpression of Usp27x in human melanoma cells leads to loss of the cFLIPL protein and sensitizes to TNF and pIC induced apoptosis through enhanced processing of caspase-8." (PMID 35044632, 2022). "Immunoprecipitation of induced GFP-tagged Usp27xL (GFP-IP) confirmed the presence of Usp27x in complex with RIPK1 in WM1158 melanoma cells (the same was seen in 1205Lu cells overexpressing GFP-mUsp27xS, data not shown) independently of TNF treatment." (PMID 35044632, 2022). "We used this melanoma cell model to test whether expression of Usp27x can also control apoptosis-induction through TLR3." (PMID 35044632, 2022). "To compare the biological activity of human and mouse Usp27x isoforms during TNF/pIC treatment, we generated 1205Lu and WM1158 melanoma cells inducibly expressing either mUsp27xS or hUsp27xL." (PMID 35044632, 2022).
viral infection (1 paper, 2020). "Of note, by measuring levels of USP27X transcripts in multiple time points after viral infection, we found that expression of USP27X displayed a constant pattern, at least, at transcriptional levels." (PMID 32027733, 2020).
tumor (11 papers, 2019 to 2025). "The regulatory function of USP27X has been implicated in multiple types of tumor progression, with our research focusing on its potential involvement in the development of BC." (PMID 38030604, 2023). "Conversely, the deficiency of USP27X results in CBX2 degradation, indicating a tumor-suppressive role for USP27X in restraining cancer progression." (PMID 38030604, 2023). "In vivo experiments also demonstrated that knockdown of USP27X suppressed tumor proliferation in xenograft models, while overexpression of USP27X promoted tumor proliferation in BT549 xenograft models." (PMID 38030604, 2023). "Lately, DUB3, OTUB1, and USP27X have been identified as specific DUBs to stabilize Snail and play important roles in Snail-mediated tumor metastasis." (PMID 31998374, 2019). "DUB3, OTUB1, and USP27X have been identified as specific DUBs to stabilize Snail and play important roles in Snail-mediated tumor metastasis." (PMID 31998374, 2019). "The results of this study indicate that knockdown of USP27X in MDA-MB-231 cells inhibits proliferation, whereas overexpression of USP27X in BT549 cells promotes tumor growth." (PMID 38030604, 2023). "In this context, RNA-sequencing analysis of OS cells and mesenchymal stem cells differentiated or not differentiated into osteoblasts reveals increased expression of four USPs in OS tumor cells: USP6, USP27x, USP41 and USP43." (PMID 34571917, 2021). "In the present study, by comparing the expression of the 56 USPs described in the literature, in seven OS cell lines and in mesenchymal stem cells or osteoblasts, we identified four USPs: USP43, USP41, USP27x and USP6, with increased expression in OS tumor cell lines." (PMID 34571917, 2021).
cancer (6 papers, 2020 to 2023). A tumor composed of atypical neoplastic, often pleomorphic cells that invade other tissues. "Here we report on the activity of Usp27x during its experimental expression in human cancer cell lines." (PMID 35044632, 2022). "Different types of cancer may present unique molecular characteristics and signaling pathways, thus the impact of USP27X and CBX2 could vary." (PMID 38030604, 2023). "Likewise, several DUBs including DUB3, OTUB1, USP1, and USP27X have been reported to be capable of stabilizing Snail1 and promoting cancer progression, which also indicates the preference of Snail1 towards different DUBs within assorted cellular contexts and milieus." (PMID 32968046, 2020). "Regarding the four USPs that we have shown increased expression in OS cells, USP27x and USP43 are involved in the control of EMT and thus metastatic progression in various cancers." (PMID 34571917, 2021). "Furthermore, to confirm the clinical significance and therapeutic potential of targeting USP27X and CBX2 in cancer treatment, more extensive clinical studies and functional preclinical studies are required." (PMID 38030604, 2023). "Additionally, our study is limited to BC, and further investigations are necessary to determine the role of USP27X and the GSK3β-USP27X-CBX2 axis in other types of cancer." (PMID 38030604, 2023). "The discovery of USP27X as a deubiquitinating enzyme for CBX2 sheds light on the regulatory mechanisms controlling its stability, providing potential therapeutic targets for aggressive cancers." (PMID 38030604, 2023). "USP27x and USP41 have also been described to modulate cell proliferation in cancer cells." (PMID 34571917, 2021). "We have identified Usp27x as a DUB capable of deubiquitinating and stabilizing the pro-apoptotic BCL2 family member Bim in conditions of active ERK signalling, protecting it from proteasomal degradation and leading to sensitization of human cancer cells to apoptosis." (PMID 35044632, 2022).
infection (1 paper, 2020). The state of being infected such as from the introduction of a foreign agent such as serum, vaccine, antigenic substance or organism. "Moreover, immunostaining showed significant overlapping signals between overexpressed USP27X and RIG-I in HEK293T cells in the presence or absence of SeV or VSVΔM51-GFP infection." (PMID 32027733, 2020).
USP27X also shares sentences with these, for which no sentence is quoted: Anxiety (1 paper); autism spectrum disorder (1); autoimmune disease (1); developmental delay (1); glioma (1); Intellectual disability (1); liver cancer (1); lung adenocarcinoma (1); osteosarcoma (1); X-linked intellectual disability (1).